MTA1 (metastasis associated 1)
Diseases named in the same sentence as MTA1 in open-access papers (continued):
Sharing a sentence is not in itself a finding about the gene and the disease.
breast carcinoma (continued). "In this study, we investigated depressive effect on MTA1 by MTA1-specific short hairpin RNA(shRNA) expression plasmids in human breast cancer cell lines MDA-MB-231 and MCF-7, and effect on protein levels of ER alpha, MMP-9, cyclinD1, and tumor cell invasion, proliferation." (PMID 21595884, 2011). "The shRNA interference targeted against MTA1 may have potential therapeutic utility in human breast cancer." (PMID 21595884, 2011). "In breast cancer exosomes, fibronectin is involved in promoting metastasis via EMT and production of pro-inflammatory cytokines and MMP-9, metastasis-associated protein 1 (MTA1) is linked to enhanced metastatic potential and unfavourable prognosis in breast cancer patients." (PMID 38200509, 2024). "However, the role of MTA1 in breast cancer related to bone metastasis requires further analysis." (PMID 35534547, 2022). "Importantly, pharmacological or genetic inhibition of autophagy restores tamoxifen sensitivity, indicating that autophagy inhibitory strategies could be considered for tamoxifen resistant, high MTA1 expressing breast cancer." (PMID 32878084, 2020). "Therefore, the inhibitory role of MTA1 in ZR-75-30 cells may be due to the specific context in this cell line or in luminal B breast cancer." (PMID 30642362, 2019). "Moreover, recent study demonstrated that IFI16 was involved in the MTA1-mediated repressor complex may contribute to the epigenetic repression of ERα expression in ERα− breast cancer." (PMID 28415616, 2017). "Leptin activates Wnt1 signaling by upregulating MTA1 expression, which induces EMT in breast cancer cells." (PMID 40565190, 2025). "In conclusion, leptin was found to upregulate MTA1 expression via the Ob-R/STAT3 signaling pathway, which in turn promotes VM by regulating the expression of VM-related proteins in breast cancer cells." (PMID 40565190, 2025). "Consequently, leptin is hypothesized to promote VM in breast cancer cells by interacting with MTA1." (PMID 40565190, 2025). "To further explore the predictive performance of MTA1, MTA3, and TRIM21 in the prognosis of patients with breast cancer, we performed immunohistochemical staining." (PMID 39154024, 2024). "We found that MTA1 and MTA3 are recognized by specific transcription factors and play opposing roles in breast cancer." (PMID 39154024, 2024). "qChIP-dependent promoter walk experiments showed that, in breast cancer cells, ERα was mainly enriched in the −800 to −200 section of the TRIM21 promoter, MTA1 was mainly enriched in the −1 400 to −500 region of the TRIM21 promoter." (PMID 39154024, 2024). "Kaplan–Meier survival analysis displayed that higher MTA1 expression level is detrimental to RFS and OS in breast cancer patients." (PMID 39154024, 2024). "Our previous study showed that NuRD (MTA1) and NuRD (MTA3) form an antagonism that potentially regulates breast cancer development and progression." (PMID 39154024, 2024). "Estrogen disrupted the balance between MTA1 and MTA3, as well as between MTA1 and TRIM21, thereby affecting stemness and the EMT processes in breast cancer." (PMID 39154024, 2024). "Together, these results suggest that MTA1 promotes EMT and stemness in breast cancer, while MTA3 exerts an opposite effect." (PMID 39154024, 2024). "It has been reported in the literature that RUNX2 is able to recruit the NuRD (MTA1)/CRL4B complex and accelerate breast cancer progression and bone metastasis and RUNX2 is also associated with breast cancer drug resistance." (PMID 38885076, 2024). "The crosstalk between MTA1 and MTA3 regulates the malignancy of breast cancer cells, including proliferation, invasion, EMT, and stemness." (PMID 39154024, 2024). "Growth curve measurements indicated that CXXC5, CUL4B, or MTA1 stable knockdown reduced the growth ability of breast cancer cells and that CXXC5, CUL4B, or MTA1 overexpression enhanced the growth of MCF-7 cells." (PMID 36539038, 2023).
breast carcinoma (continued). "In order to gain further support for the notion that the RUNX2/NuRD(MTA1)/CRL4B complex promotes the EMT and bone metastasis of breast cancer cells through the transcriptional repression of target genes, indicated experiments were performed." (PMID 35534547, 2022). "We demonstrate that the RUNX2/NuRD(MTA1)/CRL4B complex promotes the proliferation, invasion, tumorigenesis, bone metastasis, cancer stemness of breast cancer in vitro and in vivo." (PMID 35534547, 2022). "Our results indicated that RUNX2/NuRD(MTA1)/CRL4B complex suppressed invasion, migration, and bone metastasis of breast cancer cells through inhibiting PPARα." (PMID 35534547, 2022). "The chemotactic migration assay and cancer cell–bone matrix adhesion assay indicated that depletion of RUNX2, MTA1, or CUL4B hampered breast cancer cell metastasis to the bone, while overexpression of RUNX2, MTA1, or CUL4B resulted in the opposite trend." (PMID 35534547, 2022). "In order to further elucidate the physical and functional interactions among RUNX2, NuRD(MTA1), and CRL4B, we investigated the role of the RUNX2/NuRD(MTA1)/CRL4B complex in terms of EMT, stemness, and bone metastasis of breast cancer." (PMID 35534547, 2022). "Our previous studies demonstrated that the NuRD(MTA1)/CRL4B complex and the SIRT1/CRL4B complex promote stemness and EMT in breast cancer and pancreatic cancer, respectively." (PMID 35534547, 2022). "PPARα and SOD2, which inhibited breast cancer bone metastasis, were found to be the target genes of the RUNX2/NuRD(MTA1)/CRL4B complex." (PMID 35534547, 2022). "Thus, we investigated whether RUNX2 or MTA1 affect stem-like phenotypes in breast cancer cells." (PMID 35534547, 2022). "To further confirm this functional link, we investigated the influence of CUL4B, MTA1, Snail, and ZEB2 on the cellular behavior of breast cancer cells in vitro using transwell invasion assays." (PMID 34026424, 2021). "We analysed the correlations between lymph node metastasis from breast cancer, pathological stage and the expression levels of FOXP3 and MTA1." (PMID 34307133, 2021). "Although in colony formation assay, MTA1 overexpression could partially reduce the colony formation capacity of SET7/9-deficient cells, more evidences are needed to confirm whether more potential target genes including MTA1 are involved in the breast cancer progress." (PMID 32102992, 2020). "We found that the mRNA levels of VEGF, MTA1, PEG10 and hTERT in the PRKD3‐knockout breast cancer cells were lower than the ones in the parental cells." (PMID 31944568, 2020). "TICs sorted from the tumor population in MMT murine breast cancer were found to be enriched in activated HSF1 phosphorylated at S326 as well as in downstream products, such as Hsp72 and MTA1." (PMID 32331382, 2020). "We also found that knocking out PRKD3 in the breast cancer cells led to the down‐regulation of the c‐MYC target genes such as VEGF, MTA1, PEG10 and hTERT and c‐MYC‐related genes such as CCND, CCNE and E2F." (PMID 31944568, 2020). "MTA1 and MTA2 have both been reported to be pivotal for epithelial-mesenchymal transition (EMT) and metastasis of breast cancer, while MTA3 has been reported to inhibit EMT." (PMID 30642362, 2019). "CRISPR/Cas9 genetic engineering was implemented to knockout MTA1 in MCF7 and MDA-MB-231 breast cancer cells." (PMID 30782165, 2019). "In addition, because exosomes can be isolated from various body fluids it would be of great interest to determine whether MTA1 is present in exosomes isolated from the blood of breast cancer patients or other cancer patients in general, serving as circulating biomarker for diagnosis or prognosis." (PMID 30782165, 2019). "Transwell assays were used to assess the roles of MTA1 and MTA2 in the metastasis of ZR-75-30 luminal B breast cancer cells in vitro." (PMID 30642362, 2019). "MTA1 and MTA2 play opposing roles in the metastasis of ZR-75-30 luminal B breast cancer cells in vitro." (PMID 30642362, 2019).
breast carcinoma (continued). "Both being potent breast cancer metastasis-promoting factors of the MTA family, the difference and relationship between MTA1 and MTA2 remain an enigma because of insufficient investigations." (PMID 30642362, 2019). "Specifically, several subunits of NuRD, such as MTA1, MTA3, and Mi-2 can directly control the cancer invasive growth, epithelial-to-mesenchymal transition, and metastasis in breast cancer." (PMID 29625565, 2018). "In brief, findings presented here identified an upstream regulatory role of MTA1 coregulator in controlling the expression of DNMT3a and IGFBP3 in cancer cells and possibly modifying the biology of breast cancer progression." (PMID 28393842, 2017). "It has been shown that MTA1 together with IFI16 and class II HDACs was recruited and formed a complex, resulting in the epigenetic repression of ERα in ERα− breast cancer cells." (PMID 28415616, 2017). "Nevertheless, in opposite to MTA1 and MTA2, MTA3 was reported to have different expression pattern and function in human malignancies, which was first identified in human breast cancer." (PMID 28418887, 2017). "We first searched for possible correlations between MTA1, DNMT3a, and IGFBP3 using eight breast cancer datasets." (PMID 28393842, 2017). "It has been shown that MTA1 in complex with IFI16 and HDACs contributes to epigenetic repression of ERα in ERα− breast cancer cells." (PMID 28415616, 2017). "Our study showed that E2 negatively regulated miR-30c and induced its target gene, MTA-1, in EC cells, a regulatory effect that was also exhibited by miR-140 and its target gene, SOX2, in breast cancer cells." (PMID 24595016, 2014). "After transfection with the recombinant plasmid, the breast cancer cell lines MDA-MB-231 and MCF-7 showed green luminescence(green fluorescent protein, GFP), suggesting the correct expression of pGenesil-1/MTA1 shRNA." (PMID 21595884, 2011). "However, the mechanisms by which MTA1 and MTA3 play important roles in stem cell-like properties and EMT in breast cancer remain poorly understood." (PMID 39154024, 2024). "MTA1 expression was significantly negatively correlated and MTA3 expression in breast cancer." (PMID 39154024, 2024). "Additionally, in breast cancer, RUNX2 recruits the NuRD(MTA1)/CRL4B complex to catalyze histone deacetylation and ubiquitination, affecting a cohort of key genes including PPARα and SOD2, which play pivotal roles in promoting EMT and metastasis." (PMID 38430423, 2024). "The NuRD (MTA1) complex promotes EMT through transcriptional repression of peroxisome proliferator-activated receptor α (PPARα) and superoxide dismutase 2 (SOD2) in breast cancer." (PMID 39154024, 2024). "In this study, we aimed to investigate the roles of MTA1, MTA3, and tripartite motif-containing 21 (TRIM21) in the proliferation, invasion, epithelial-mesenchymal transition (EMT), and stem cell-like properties of breast cancer cells in vivo and in vitro." (PMID 39154024, 2024). "Similarly, we found that CRL4B interacted with multiple histone deacetylase (HDAC)-containing co-repressor complexes, such as NuRD(MTA1) complex, promoting the EMT process and tumorigenesis in breast cancer." (PMID 35534547, 2022). "Functional experiments demonstrated that RUNX2/NuRD(MTA1)/CRL4B complex could promote EMT and bone metastasis by inhibiting the expression of PPARα and SOD2 in breast cancer." (PMID 35534547, 2022). "Therefore, MTA1–OGT interaction and its aberrant O-GlcNAcylation protected the breast cancer cells against genotoxic stress, leading to drug resistance." (PMID 36291918, 2022). "In vitro and in vivo experiments were used to determine whether the regulation of MTA1 by FOXP3 affected the invasion and migration of breast cancer cells." (PMID 34307133, 2021).
breast carcinoma (continued). "We investigated the roles of MTA1 and MTA2 in the metastasis of the ZR-75-30 luminal B breast cancer cell line, and we found that the overexpression of MTA1 inhibits the metastasis of ZR-75-30 cells by downregulating MTA2, which has not been clarified previously." (PMID 30642362, 2019). "In this study, we aimed to examine the different roles that MTA1 and MTA2 may play in breast cancer metastasis and investigate their relationship." (PMID 30642362, 2019). "Both MTA1 and MTA2 have been reported to promote EMT and breast cancer metastasis." (PMID 30642362, 2019). "Elucidating the difference between MTA1 and MTA2 may lead to an improved understanding of breast cancer metastasis." (PMID 30642362, 2019). "In addition, MTA1 overexpression correlates well with low levels of DNMT3a which, in turn also correlates with a high IGFBP3 status in breast cancer patients and predicts a poor clinical outcome for breast cancer patients." (PMID 28393842, 2017). "We found that increased levels of MTA1 correlate well with an elevated level of IGFBP3 as well as low DNMT3a and this may result in poor prognosis of breast cancer patients." (PMID 28393842, 2017). "Thus, we then determined the potential role of MTA1 in Z-LIG mediated re-expression of ERα and re-sensitivity to TAM in ERα− breast cancer cells." (PMID 28415616, 2017). "Previous study has been shown that MTA1 is negatively related to ERα expression and its recruitment to the ERpro315 region of the ESR1 promoter contributes to the epigenetic repression of ERα expression in ERα− breast cancer cells." (PMID 28415616, 2017). "Also MTA1, a known corepressor for ERɑ, was shown to function as a coactivator for the gene BCAS3 that was described to be overexpressed and amplified in breast cancer." (PMID 29312638, 2017). "Several studies found that MTA1-positive expression was not correlated with OS in patients with esophageal squamous cell carcinoma and breast cancer." (PMID 28570554, 2017). "Our finding that HNK modulates Akt, GSK3β, and β-catenin, key components of leptin-signaling network in breast cancer cells, prompted us to further explore whether HNK treatment can also inhibit MTA1, Wnt1, β-catenin and cyclin D1 in the presence of leptin." (PMID 26036628, 2015). "We demonstrated that in breast cancer cells, CXXC5 is responsible for initiating the transcriptional repression of TSC1, followed by monoubiquitination of H2AK119 by the CRL4B complex and NuRD (MTA1) complex–mediated histone deacetylation, which create a repressive chromatin environment." (PMID 36539038, 2023). "In conclusion, we demonstrated that RUNX2 could cooperate with NuRD(MTA1)/CRL4B complex and acted as an inducer in various biological processes, including cell proliferation, invasion, bone metastasis, as well as cancer stemness of breast cancer." (PMID 35534547, 2022). "Therefore, it is suggested that RUNX2/NuRD(MTA1)/CRL4B complex might activate the IL-17 signaling pathway and multiple cytokines to induce bone metastasis in breast cancer." (PMID 35534547, 2022). "Finally, MTA1/IFI16/HDACs corepressor complex was identified as the key epigenetic mechanism regulated by Z-LIG for the reactivation of ERα and subsequent restoration of TAM sensitivity of ERα− breast cancer cells." (PMID 28415616, 2017). "Earlier investigations stated that MTA1s, a short version of MTA1, is located in the cytoplasm, binding to ER-α and inhibiting its nuclear function by transforming it to cytoplasm in breast cancer cells; thus, non-genomic function of ER-α occurs in the cytoplasm, such as stimulation of MAPK." (PMID 26878004, 2016). "In addition, a series of work showed that MTA1 could promote tumor cell invasion and metastasis in non-small cell lung cancer, colon cancer, gastric cancer and breast cancer." (PMID 28418887, 2017). "In addition, such future studies may include MTA1 knockdown with or without DNMT3a in breast cancer cells." (PMID 28393842, 2017).
breast carcinoma (continued). "In conclusion, our research provides mechanistic understandings that the negative feedback loops between MTA1 and MTA3, MTA1, and TRIM21 in response to estrogen are initiated to regulate cancer stem cell fate and EMT in breast cancer." (PMID 39154024, 2024). "The published breast cancer dataset (GSE48390) revealed a positive correlation between RUNX2, MTA1 and CUL4B, and negative correlations among RUNX2/MTA1/CUL4B and PPARα/SOD2." (PMID 35534547, 2022). "Scoring of the IHC staining of MTA1 and MTA2 indicated a negative correlation between the protein level of MTA1 and MTA2 in luminal B breast cancer tissues (P < 0.05), and representative images are shown." (PMID 30642362, 2019). "However, neither overexpression of MTA1 nor inhibition of MTA1 expression had any detectable effect on cell cycle progression or proliferation of HaCaT keratinocytes, MCF-7, or MDA-MB-435 breast cancer cells." (PMID 14735193, 2004). "However, after inhibiting mRNA levels of MTA1, protein expression of ER alpha, MMP-9, cyclinD1 and the changes of cancer cells invasiveness, proliferation, cells cycle were no statistical difference in ER-positive human breast cancer cell lines MCF-7 (P > 0.05)." (PMID 21595884, 2011).